CDX2 (caudal type homeobox 2)
Diseases named in the same sentence as CDX2 in open-access papers (continued):
Sharing a sentence is not in itself a finding about the gene and the disease.
endometrial carcinoma (4 papers, 2015 to 2024). A malignant tumor arising from the epithelium that lines the cavity of the uterine body. "Histological examination confirmed rectal mass as a metastatic adenocarcinoma, not a primary rectal cancer, with immunohistochemical features of endometrial carcinoma CK7+, ER+, CDX2−, CK20−, antivimentin Ab+, and PAX 8+ (focally)." (PMID 26783488, 2015).
esophageal cancer (4 papers, 2009 to 2022). A primary or metastatic malignant neoplasm involving the esophagus. "Studies assessing CDX2 are mainly related to digestive tract tumors, and reveal an oncogenic role for CDX2 in esophageal cancer, but a suppressor function in colorectal, gastric, and breast cancers." (PMID 33621200, 2021).
gastrointestinal carcinoma (4 papers, 2009 to 2022). "MTBF acts in the muscle regulation of the myostatin gene, while CDX2 is mainly expressed in the gut although its ectopic expression was also reported in cases of non-gastrointestinal carcinomas." (PMID 19523210, 2009).
inflammatory bowel disease (4 papers, 2014 to 2024). A spectrum of small and large bowel inflammatory diseases of unknown etiology. "Existing literature already indicates a correlation between Cdx2 SNPs and the onset of inflammatory bowel disease." (PMID 39685734, 2024). "Likewise, CDX2 is also involved in regulation of expression of Claudin genes and is involved in inflammatory bowel disease and cancer." (PMID 30087389, 2018).
invasive carcinoma (4 papers, 2017 to 2024). A carcinoma that is not confined to the epithelium, and has spread to the surrounding stroma. "In our present case, confirming its tumor suppressor role, CDX2 exhibited strong and diffuse expression in IM, dysplasia, carcinoma in situ, and well-differentiated invasive carcinoma, while displaying focal and weak expression in poorly differentiated areas of signet ring cells." (PMID 39036214, 2024). "The immunohistochemical markers CDX2 and CK20 in IPNB and CK20 in IPNG were associated with invasive carcinoma, which suggests that intestinal metaplasia participated in tumorigenesis, and some internal molecular changes of this pathological process also play a role in tumor progression." (PMID 28415560, 2017). "For the diagnosis of primary CRC in resection specimen, CDX2 is not frequently used, because the vast majority of CRCs are accompanied by adenomatous precursor lesions that are diagnostic of primary CRC in combination with a morphologically compatible invasive carcinoma component." (PMID 34616012, 2021). "The pathological findings revealed invasive carcinoma derived from IPNB, and immunohistochemistry revealed positive expression of MUC1, MUC5AC, and MUC6, but negative expression of CDX2 and MUC2." (PMID 33097064, 2020).
mucinous ovarian cancer (4 papers, 2016 to 2023). An invasive malignant neoplasm that arises from the ovary and is characterized by the presence of malignant epithelial cells that contain intracytoplasmic mucin and may resemble the epithelial cells of the endocervix or gastrointestinal tract. "Another recent study showed that Reg IV expression was observed in all CDX2 positive cases of ovarian mucinous cancer." (PMID 33639844, 2021). "The differential diagnosis of MOC requires a combination of other indicators such as CK7, CK20, CDX2, PAX8, SATB2, and claudin 18.2, which may further reduce the misdiagnosis and missed diagnosis of mucinous ovarian cancer." (PMID 37664708, 2023).
Paget disease (4 papers, 2022 to 2024). A malignant neoplasm composed of large cells with large nuclei, prominent nucleoli, and abundant pale cytoplasm (Paget cells). "Their study demonstrated the use of staining patterns of CK7, GCDFP‐15, CK20, MUC2, and CDX2 to help distinguish Paget's disease from anorectal adenocarcinoma." (PMID 39253370, 2024).
polyp (4 papers, 2014 to 2020). A usually exophytic mass attached to the underlying tissue by a broad base or a thin stalk. "On the other hand, surface epithelium in the lower side of the polyp still preserved intestinal nature, containing CDX2-positive nuclei and MUC2-positive goblet cells." (PMID 24422755, 2014). "The enteroids were isolated from the uninvolved region (normal, no polyp) and the involved/affected regions (polyps) of the colonic specimens of CDX2 Cre APCMin/+ mice." (PMID 32872214, 2020).
renal carcinoma (4 papers, 2014 to 2023). A carcinoma arising from the epithelium of the renal parenchyma or the renal pelvis. "The purpose of this review is to analyze the association of some common VDR gene polymorphisms, such as Taq1, Fok1, Apa1, Bsm1, Cdx2, poly(A) and Bgl1, with breast and renal cancers." (PMID 24297042, 2014). "In contrast, PAX8, TTF1, and CDX2, markers for renal carcinomas, pulmonary and thyroid neoplasms, and small intestine or the appendix, respectively, were constantly negative in all RenNETs of our series and in the cases of the literature." (PMID 37405461, 2023). "Furthermore, the IHC for CK20, CDx2, TTF1, CD10 and Vimentin showed a negative result, thus excluding metastases from gastrointestinal, lung, thyroid, renal cancer as well as sarcoma, respectively." (PMID 33912469, 2021).
small bowel adenocarcinoma (4 papers, 2020 to 2025). "CDX2 is a reliable marker for gastrointestinal origin, particularly in distinguishing primary small bowel adenocarcinoma from metastatic adenocarcinomas of other origins." (PMID 39434934, 2024). "Similarly, a lack of CDX2 expression is sometimes observed in small intestinal adenocarcinomas." (PMID 32867793, 2020).
thyroid cancer (4 papers, 2016 to 2024). "Furthermore, morular areas of cribriform morular thyroid carcinoma often lack TTF-1 expression but have CDX2, CD5, and CK5." (PMID 38835742, 2024). "Glomeruloid variant of follicular thyroid carcinoma can be mistaken for cribriform-morular thyroid carcinoma, but lack of CDX2 and CD10-positive morules and absence of nuclear β-catenin positivity can help in this distinction." (PMID 32632840, 2020).
ampullary cancers (3 papers, 2023 to 2025). "Originally described in ampullary carcinoma, the INT versus PB dichotomy is defined by distinct H&E architecture and immunophenotype (e.g., CDX2/MUC1 patterns) and has been linked to clinical behavior." (PMID 41301018, 2025). "Although MUC1 has also been suggested to distinguish the pancreatobiliary subtypes of ampullary carcinomas, its use has not been independently validated and it mostly has been examined in conjunction with CK or CDX2." (PMID 38893239, 2024). "In an Italian report of 53 resected ampullary cancers, the expressions of CDX2 were found in 60% (32/53) of the total cases, where 30% of the PB type (9/30) and 100% INT type (23/23), showed a positive staining of the CDX2 protein." (PMID 37504367, 2023).
anal adenocarcinomas (3 papers, 2018 to 2025). "Beside T-cell subsets, epithelial PD-L1 expression was also statistically more important in anal adenocarcinomas arising from the anal glands/transitional zone compared to their Krt20/CDX2-positive counterparts." (PMID 29700411, 2018). "Positive CK20, CDX2, villin, and SATB2 confirmed adenocarcinoma with intestinal differentiation, while PAX8 negativity ruled out ovarian malignancy, concluding that the lymphadenopathy was likely due to metastasis of anal adenocarcinoma." (PMID 41573493, 2025).
cervical carcinoma (3 papers, 2012 to 2020). A carcinoma arising from either the exocervical squamous epithelium or the endocervical glandular epithelium. "The present case is a unique cervical cancer, consisting of neuroepithelial components positive for CD99 and synaptophysin, immature / atypical intestinal glands positive for SALL4 and CDX-2, cartilage cells, and rhabdomyosarcoma, resembling sinonasal TCS." (PMID 31684979, 2019).
cyst (3 papers, 2011 to 2025). A sac-like closed membranous structure that may be empty or contain fluid or amorphous material. "Based on gross morphology using a stereomicroscope and expression of CDX2 in the cyst wall, we excluded the possibility of the blood vessels." (PMID 38892233, 2024). "Similar to the epithelial cultures, E-cadherin and CDX-2 were positive in the cell lining in the cyst wall, indicating the presence of intestinal epithelium." (PMID 22125602, 2011). "We also stained the cystic lesions with CDX2, CK18, and YAP-1, markers of trophectoderm, and we found that all of those markers were expressed in the cyst wall." (PMID 38892233, 2024).
endometrial adenocarcinoma (3 papers, 2016 to 2025). "Strikingly, we noticed that HEMO prominent areas in endometrium adenocarcinoma matched with morules clearly identified in HES and positively stained with CDX2, known as being expressed in these typical elements." (PMID 34318590, 2022). "While primary bowel adenocarcinomas typically express CDX2, CK7, and CK20, endometrial adenocarcinomas are negative for CDX2 and CK20." (PMID 40248443, 2025). "Subsequent surgical resection confirmed metastatic endometrial adenocarcinoma based on immunohistochemical analysis, which demonstrated positivity for estrogen receptor and paired box gene 8, while CK7, CK20, and CDX2 were negative." (PMID 40248443, 2025).
epithelioid mesothelioma (3 papers, 2017 to 2026). "Laparoscopic palliative tumor resection and peritoneal effusion drainage were performed, and postoperative pathology/immunohistochemistry (CK+, CR+, CK5/6+, D2-40+, WT1+, CD20-, CDX2-) confirmed epithelioid mesothelioma of the omentum." (PMID 41970397, 2026).
intestinal cancer (3 papers, 2013 to 2020). "We are not aware of other vulvar intestinal cancers expressing CDX2, as this marker was not investigated in the published studies." (PMID 24307962, 2013).
intraepithelial neoplasia (3 papers, 2020 to 2023). A precancerous neoplastic process that affects the squamous, glandular, or transitional cell epithelium without evidence of invasion. "The expressions of villin and CDX2 were negative in the normal gastric mucosa, while various degrees of villin and CDX2 positive expressions were observed in the intraepithelial neoplasia period of glandular atrophy." (PMID 37968594, 2023).
myeloid leukemia (3 papers, 2012 to 2020). A clonal proliferation of myeloid cells and their precursors in the bone marrow, peripheral blood, and spleen. "Furthermore, reactivation of KLF4 expression through modulation of PPARγ signaling, exerted a multifaceted tumor-suppressive effect in CDX2 positive myeloid leukemia cell lines and primary AML blasts, suggesting PPARγ agonists as a therapeutic modality in a large proportion of AML patients." (PMID 30542286, 2018).
non-small cell lung carcinoma (3 papers, 2016 to 2020). A group of at least three distinct histological types of lung cancer, including non-small cell squamous cell carcinoma, adenocarcinoma, and large cell carcinoma. "Although a definitive link to BE or EAC has not been established, miR-181b, shown to increase tumor metastasis in a mouse model of non-small cell lung carcinoma (NSCLC), is upregulated in both metastatic human NSCLC and breast cancer and is regulated by CDX2." (PMID 29487725, 2018).
pancreatic adenocarcinoma (3 papers, 2012 to 2025). "Among the 32 cases of pancreatic adenocarcinoma, only 5 cases were focally positive for CDX2 (χ2 = 33.462; p < 0.001)." (PMID 22268990, 2012). "CDX2 was expressed in 114 of 118 (97%) colorectal, 36 of 59 (61%) gastric, and 5 of 32 (16%) pancreatic adenocarcinomas (χ2 = 93.576; p < 0.001)." (PMID 22268990, 2012). "CDX2 was expressed in 114 of 118 (97%) colorectal, 36 of 59 (61%) gastric, and 5 of 32(16%) pancreatic adenocarcinomas." (PMID 22268990, 2012). "In our study, CDX2 was expressed in 114 of 118 (97%) colorectal, 36 of 59 (61%) gastric, and 5 of 32(16%) pancreatic adenocarcinomas." (PMID 22268990, 2012). "In the present study, among the 32 cases of pancreatic adenocarcinomas, only 5 cases were focally positive for CDX2." (PMID 22268990, 2012). "CK7/CK20 staining pattern and CDX2 expression were evaluated in 118 cases of colorectal, 59 cases of gastric, and 32 cases of pancreatic adenocarcinomas." (PMID 22268990, 2012). "While CDX2 appears to have somewhat higher sensitivity for CRC than SATB2, the previous studies have indicated that SATB2 has higher specificity for CRC, as CDX2 is frequently also expressed by adenocarcinomas of the pancreas or the upper gastrointestinal tract among others." (PMID 39998677, 2025). "CDX2 is weakly positive in approximately one third of pancreatic adenocarcinomas." (PMID 39535001, 2024). "In the present study, we examined the expression profiles of CK7, CK20, and CDX2 immunohistochemical markers in primary colorectal, gastric and pancreatic adenocarcinomas in consideration of the potential applicability of these markers in the clinical context of metastatic adenocarcinomas." (PMID 22268990, 2012). "Among the 32 cases of pancreatic adenocarcinoma, only 5 cases were focally positive for CDX2." (PMID 22268990, 2012). "In gastric and pancreatic adenocarcinomas, CK7+/CK20+/CDX2+ (21/59, 36%) and CK7+/CK20-/CDX2- (21/32, 66%) were the most common patterns respectively." (PMID 22268990, 2012).
prostate tumors (3 papers, 2017 to 2025). "We anticipate that there is a similar synergy between FOXA1, HOXB13 and CDX2 TFs in remodelling the chromatin structure in high-grade prostate tumours." (PMID 34911933, 2021). "In parallel to our observations, we found FOXA1, HOXB13 and CDX2 to be highly enriched in prostate tumours with primary Gleason pattern 4 (Gleason score 4 + 4 and 4 + 5 patients) as compared to tumours that are predominantly Gleason pattern 3 (Gleason score 3 + 4)." (PMID 34911933, 2021). "We found low-grade prostate tumours were significantly enriched for the AP-1 family of TF binding sites (JUN, JUNB, JUND and FOS, FOSB and FRA1, and the closely related activating TFs: ATF and CREB), in contrast to high-grade prostate tumours that were enriched for FOXA1, HOXB13 and CDX2." (PMID 34911933, 2021).
psoriasis (3 papers, 2021 to 2025). An autoimmune condition characterized by red, well-delineated plaques with silvery scales that are usually on the extensor surfaces and scalp. "Genetic polymorphisms in the VDR, particularly the TaaI/Cdx-2 (rs11568820) single-nucleotide polymorphism (SNP), are associated with susceptibility to psoriasis and other immune-mediated dermatoses." (PMID 40681996, 2025). "Until now, five VDR polymorphisms, FokI, ApaI, BsmI, TaqI and TaaI/Cdx2, have been studied in psoriasis, with contradicting results." (PMID 34208603, 2021). "We found that the frequency of the TaaI/Cdx-2 GG genotype was significantly higher in psoriasis patients and was associated with regulation of IL-17 and IL-23 concentration." (PMID 34208603, 2021). "Furthermore, these TaaI/Cdx-2 variants have a notable impact on the response to phototherapy in psoriasis patients." (PMID 40681996, 2025). "Moreover, TaaI/Cdx-2 variants have a significant effect on the response to phototherapy amongst patients with psoriasis and regulation of inflammatory response via decrease of IL-17 and IL-23 level after UVB phototherapy in the Polish population." (PMID 34208603, 2021). "The common rs11568820 AA (TaaI/Cdx-2) variant might have a significant effect on the response to therapies amongst patients with psoriasis." (PMID 34208603, 2021). "The TaaI/Cdx-2 AA variant might have a significant effect on the response to phototherapy amongst patients with psoriasis." (PMID 34208603, 2021). "We found that the frequency of the TaaI/Cdx-2 GG genotype was significantly higher in psoriasis patients than in controls." (PMID 34208603, 2021). "Moreover, TaaI/Cdx-2 AA might have a significant effect on the response to phototherapy amongst patients with psoriasis." (PMID 34208603, 2021). "TNF alpha concentration in patients with psoriasis decreases after UVB irradiation, independent of polymorphisms in the VDR gene, except for the presence of the TaaI/Cdx-2 AA genotype and TaqI TT genotype." (PMID 34208603, 2021).
sarcoma (3 papers, 2015 to 2021). A usually aggressive malignant neoplasm of the soft tissue or bone. "Consistently, IHC negative for CK20, CDx2, TTF-1, CD10 and Vimentin excluded urothelial, gastrointestinal, lung, thyroid, kidney cancer and sarcoma metastasis." (PMID 33912469, 2021).
sirenomelia (3 papers, 2021 to 2023). Sirenomelia is a rare, genetic, developmental defect during embryogenesis disorder characterized by fusion of the lower limbs and associated with some degree of lower extremity reduction and persistent vitelline artery. "Recently, variants in CDX2 have also been reported in two familial aggregations with phenotype ranging from sirenomelia with different degrees of urogenital malformations to isolated imperforate anus indicating its role in caudal malformations." (PMID 36478354, 2023). "Only three pathogenic variants in human CDX2 have been described, in patients with persistent cloaca, sirenomelia and/or renal and anogenital malformations." (PMID 34671974, 2022). "However, human CDX2 gene variants have recently been associated with sirenomelia, in accordance with the function attributed to this gene in posterior body elongation and patterning." (PMID 34759958, 2021). "Strikingly, Cdx2 heterozygous conditional mutant mice show a variable phenotype that can include an imperforate anus, sirenomelia, posterior vertebral truncations, and bladder anomalies, which is similar to the human clinical phenotype." (PMID 34671974, 2022). "Interestingly, RA exposure of heterozygous conditional mutant mice resulted in the development of sirenomelia, underscoring the molecular interplay between CDX2 and RA signaling." (PMID 34671974, 2022).
urachal adenocarcinomas (3 papers, 2013 to 2018). "However, nuclear CDX2 reactivity was evident in the majority of urachal adenocarcinomas (90%) and many primary bladder adenocarcinomas (13%–83%)." (PMID 29721106, 2018). "In the present report, immunohistochemistry analysis showed positivity for CK20, Villin, and CDX-2, and negativity for ER, PR, HER-2, GCDFP-15, and CK7, which supported the diagnosis of urachal adenocarcinomas." (PMID 27583877, 2016).
Urachal carcinomas (3 papers, 2013 to 2024). "Firstly, CK20 and CDX-2 are diffusely and strongly positive in urachal carcinoma, while about 50% of urachal carcinomas are positive for CK7, so there are two possible profiles for urachal carcinoma (CK7−/CK20+/CDX2+ vs. CK7+/CK20+/CDX2+)." (PMID 23914849, 2013). "Urachal carcinomas generally exhibit positive expressions of CK7, CK20, and CDX2, with absent nuclear beta‐catenin expression." (PMID 39462217, 2024).
vascular tumor (3 papers, 2021 to 2022). "Based on LSH, CD4 expression was significantly associated with tumor location (P=0.045), tumor differentiation (P=0.007), vascular tumor thrombus (P=0.008), postoperative chemoradiotherapy (P=0.017), and CDX2 expression (P=0.011) in PDAC patients." (PMID 34367978, 2021).